ENSG00000269469 (novel protein)
Gene: Protein-coding gene on chromosome 19 (49,462,752 to 49,486,231, forward strand). Ensembl gene ENSG00000269469.
Genetic constraint (gnomAD): Missense variants: 109 observed, 99.56 expected, observed/expected ratio (o/e) 1.09, 90% interval 0.94 to 1.28. Synonymous variants: 36 observed, 37.93 expected, observed/expected ratio (o/e) 0.95, 90% interval 0.73 to 1.25.